SMARCB1 (SWI/SNF related BAF chromatin remodeling complex subunit B1)
Diseases named in the same sentence as SMARCB1 in open-access papers (continued):
Sharing a sentence is not in itself a finding about the gene and the disease.
bladder cancer (6 papers, 2021 to 2025). "As yet, our understanding regarding the impact and specific mechanisms underlying SNF5/BAF47 (it is encoded by the SMARCB1) in bladder cancer remains incomplete." (PMID 39779467, 2025). "In SMARCB1-deficient bladder cancer, STAT3 was significantly activated and facilitated tumor growth and metastasis." (PMID 39995416, 2025). "The STAT3 inhibitor TTI‐101 can inhibit the growth and metastasis of SMARCB1‐deficient bladder cancer." (PMID 39779467, 2025). "Here, we demonstrate that SMARCB1 deficiency, defined as genomic SMARCB1 copy number loss associated with reduced mRNA, drives disease progression in patients with bladder cancer by engaging STAT3." (PMID 38355560, 2024). "Here, the authors show in several preclinical models that targeting IL6/JAK/STAT3 molecular pathway is a potential therapeutic approach for SMARCB1-deficient bladder cancer." (PMID 38355560, 2024). "Overall, these findings support the clinical evaluation of STAT3 inhibitors for the treatment of SMARCB1-deficient bladder cancer." (PMID 38355560, 2024). "One study showed that low SMARCB1 expression promoted Bladder cancer growth by activating STAT3; therefore, targeting the IL6/JAK/STAT3 pathway is a potential treatment for SMARCB1-deficient tumors." (PMID 40115023, 2025). "Study have demonstrated that absence of SMARCB1 (encoding SNF5/BAF47 protein) leads to enhanced chromatin accessibility at the STAT3 promoter, which in turn triggers activation of the IL6/JAK/STAT3 pathway to facilitate the growth and spread of bladder cancer." (PMID 39779467, 2025).
colon cancer (6 papers, 2014 to 2021). "As further validation, we performed glycerol sedimentation in the HCT116 (SMARCB1-WT) colon cancer cell line." (PMID 31015438, 2019). "The vectors were lenti-viral introduced into DLD-1, a colon cancer line expressing a wild-type SMARCB1." (PMID 31586052, 2019).
liver cancer (6 papers, 2021 to 2025). An epithelial or non-epithelial malignant neoplasm that arises from the liver. "Specifically, in liver cancer, it is up-regulated and an oncogene, working as a key target and partner of SMARCB1, a common subunit of SWI/SNF chromatin remodeling complexes." (PMID 39858538, 2025). "Robust data have revealed that SMARCB1 functions as a tumour suppressor gene during cancer progression, although one study has reported a tumorigenic role in liver cancer." (PMID 34668612, 2021). "Indeed, SMARCB1 associated with the promoter region of MIR17HG in ATRT cell lines, pluripotent human germ cell tumor-derived cells and human liver cancer cells." (PMID 34439268, 2021). "The role of SMARCB1 in pediatric cancers has been well characterized as a tumor suppressor; however in adult cancers, its role appears more complex, with studies suggesting that SMARCB1 may also act as an oncogene in certain contexts, including liver cancer and melanoma." (PMID 40196006, 2025). "However, a recent study has indicated a potentially oncogenic role of SMARCB1 in liver cancer." (PMID 34668612, 2021).
NUT carcinoma (6 papers, 2018 to 2024). "The results did not support the diagnosis of squamous cell carcinoma, adenoid cystic carcinoma, SMARCB1-deficient carcinoma, undifferentiated carcinoma, or NUT carcinoma." (PMID 39319059, 2024). "SMARCB1-deficient carcinoma, SMARCA4-deficient carcinoma and NUT carcinoma were devoid of CD8+ TILs." (PMID 36140305, 2022). "The three cases SMARCB1-deficient carcinoma, SMARCA4-deficient carcinoma and NUT carcinoma may be given special attention." (PMID 36140305, 2022). "Unfortunately, for PD-SNSCC, SMARCB1-deficient carcinoma, SMARCA4-deficient carcinoma and NUT carcinoma, no follow-up data were available." (PMID 36140305, 2022). "The one case of SMARCB1-deficient carcinoma was also PD-L1 positive, while SMARCA4-deficient carcinoma and NUT carcinoma showed no expression." (PMID 36140305, 2022). "Our cohort included one case each of SMARCB1-deficient carcinoma, SMARCA4-deficient carcinoma and NUT carcinoma, unfortunately without follow-up information." (PMID 36140305, 2022).
pediatric tumors (6 papers, 2015 to 2023). "Of bound SWI/SNF family members, we have previously discussed SMARCB1 as recurrent mutation in mCRPC, and its loss as a biomarker in malignant pediatric tumors." (PMID 35550030, 2022).
Vestibular schwannoma (6 papers, 2009 to 2025). A vestibular schwannoma (also known as acoustic neuroma, acoustic neurinoma, or acoustic neurilemoma) is a benign, usually slow-growing tumor that develops from the VIIIth cranial nerve supplying the inner ear. "Further studies are, therefore, needed to investigate a possible association between unilateral vestibular schwannomas and germline SMARCB1 mutations." (PMID 27921248, 2017). "All five patients carrying a SMARCB1 mutation were sporadic patients diagnosed before 35 years of age with multiple non-vestibular schwannomas." (PMID 21255467, 2011). "Three genes centromeric to NF2 on 22q have now been found shown to account for ~ 70% of familial and ~ 30% of sporadic patients with multiple non-vestibular schwannomas: SMARCB1, LZTR1, and much less commonly DGCR8." (PMID 41160189, 2025). "To improve the clinical indications for SMARCB1 molecular screening in medical genetics practice, we evaluated its implication in a series of patients exhibiting non-vestibular schwannomas and no NF2 germline alteration." (PMID 21255467, 2011).
clear cell renal carcinoma (5 papers, 2017 to 2025). A malignant epithelial neoplasm of the kidney characterized by the presence of lipid-containing clear cells within a vascular network. "Nomenclature modifications were observed in the context of papillary and clear cell renal cancer: HLRCC nomenclature was modified to FH-deficient RCC, and renal medullary cancer has been revised to SMARCB1-deficient RCC." (PMID 38765391, 2024). "Here, we have used CRISPR-Cas9-based genetic screening to demonstrate that loss of SMARCB1, a member of the SWI/SNF chromatin remodeling complex, can confer an advantage to clear cell renal cell carcinoma (ccRCC) cells upon inhibition of the renal lineage factor PAX8." (PMID 37554444, 2023).
Medullary carcinoma (5 papers, 2015 to 2024). "A variant of this tumor known as medullary carcinoma presents most commonly in patients with sickle cell trait and is associated with the loss of SMARCB1/INI1 expression." (PMID 25905038, 2015).
metastatic tumors (5 papers, 2013 to 2026). "Conversely, Case 23 demonstrated preserved INI1 expression in both primary and metastatic tumors despite SMARCB1 heterozygous loss in the latter." (PMID 41317331, 2026). "(a) Copy number analysis of RMC models from WES identifies heterozygous loss of alleles particularly at 22q where SMARCB1 resides or low-level gains in primary and metastatic tumors." (PMID 30860482, 2019). "SMARCB1/INI1 exon amplification and sequencing revealed the presence of a homozygous exon 2 c.118C>T (Arg40X) mutation in both the primary and metastatic tumor lesions." (PMID 23510391, 2013). "Two metastatic tumors (Cases 22 and 23) harbored heterozygous SMARCB1 deletions accompanied by broad 22q losses affecting CHEK2, NF2, and EP300." (PMID 41317331, 2026). "In contrast, CNVs affecting genes involved in chromatin remodeling (e.g., SMARCB1 and ATRX) were exclusively identified in metastatic tumors." (PMID 41317331, 2026).
non-Hodgkin lymphoma (5 papers, 2018 to 2024). Distinct from Hodgkin lymphoma both morphologically and biologically, non-Hodgkin lymphoma (NHL) is characterized by the absence of Reed-Sternberg cells, can occur at any age, and usually presents as a localized or generalized lymphadenopathy associated with fever and weight loss. "This group also showed high efficacy in murine Smarcb1-negative PTCL compared to other non-Hodgkin lymphoma (NHL) cell lines." (PMID 39362842, 2024).
osteosarcoma (5 papers, 2021 to 2025). A usually aggressive malignant bone-forming mesenchymal neoplasm, predominantly affecting adolescents and young adults. "The study of the mRNA by in silico analysis confirmed that SMARCB1 expression correlates somehow with the response to chemotherapy and prognosis in osteosarcoma patients." (PMID 35583077, 2022). "The reliability would be improved by detailed analysis of SMARCB1 expression in different types of osteosarcomas." (PMID 35583077, 2022). "On the other side, much work needs to be done if we hope that we strive to provide additional therapeutic strategies for osteosarcoma patients with altered SMARCB1 gene expression." (PMID 35583077, 2022). "They found a weak SMARCB1 expression in about two-thirds of the osteosarcoma specimens in the TMA." (PMID 35583077, 2022). "Importantly, the loss of SWI/SNF binding was not seen in U2OS cells (human osteosarcoma cell line) which have SMARCB1 expressed." (PMID 33332735, 2021). "Meanwhile, higher expression levels of SMARCB1, UBQLN2, ENY2, and BAZ1B was observed in high-grade osteosarcoma prechemotherapy biopsy samples than that of MSCs." (PMID 40989695, 2025). "On the other side, much work needs to be done if we hope to provide additional therapeutic strategies for patients affected with osteosarcoma with or without altered SMARCB1 gene expression." (PMID 35583077, 2022). "They examined 114 specimens from 70 osteosarcoma patients to build a tissue microarray (TMA) and assess the staining of SMARCB1 protein using a straightforward Avidin–Biotin Complex-based immunohistochemically run assay or immunofluorescence on paraffin blocks." (PMID 35583077, 2022).
rhabdoid tumor predisposition syndrome 1 (5 papers, 2018 to 2025). Any familial rhabdoid tumor in which the cause of the disease is a mutation in the SMARCB1 gene. "Approximately 25–35% of patients with AT/RT carry a germline SMARCB1 alteration that defines the Rhabdoid Tumour Predisposition Syndrome type 1 (RTPS1; MIM #609322) [12, 13, reviewed by 14]." (PMID 40794298, 2025). "Germline whole-gene or partial gene deletions, as well as truncating mutations of SMARCB1 cause a cancer predisposition syndrome called Rhabdoid Tumor Predisposition Syndrome 1 (RTPS1; OMIM 609322)." (PMID 30123105, 2018). "SMARCB1 and SMARCA4 germline mutations define rhabdoid tumor predisposition syndrome types 1 (RTPS1) and 2 (RTPS2), respectively." (PMID 37508611, 2023).
viral infection (5 papers, 2013 to 2025). "Specifically, SMARCB1 inhibition has been shown to impair antiviral responses by disrupting cellular defenses against viral infection, whereas SP1 is known to enhance viral gene transcription, as observed in herpes simplex virus." (PMID 40770872, 2025). "PBRM1 is a chromatin modulator of the SWI/SNF chromatin remodeling complex, which includes SMARCA4, SMARCB1, SMARCC1, ARID1A, DPF2, and SMARCE1, also implicated in ACE2 expression regulation and, thus, in host cell susceptibility to viral infection." (PMID 40378209, 2025).
Wilms tumor (5 papers, 2017 to 2024). An embryonal neoplasm characterized by the presence of epithelial, mesenchymal, and blastema components. "Eighty-six percent of these cases maintained consistent class assignments over time, with the exception of two Wilms tumors with contamination as well a SMARCB1-associated tumor, a subtype currently absent from our reference." (PMID 36932241, 2023). "(b) Early passage Wilms tumor (SMARCB1 wild-type) cell line CLF_PEDS1012_T1 is not as sensitive to treatment with bortezomib compared with RMC and MRT cell lines." (PMID 30860482, 2019). "(c) Early passage Wilms tumor (SMARCB1 wild-type) cell line CLF_PEDS1012_T1 is not as sensitive to treatment with MLN2238 compared with RMC and MRT cell lines." (PMID 30860482, 2019).
adenoid cystic carcinoma (4 papers, 2021 to 2024). A malignant tumor arising from the epithelial cells. "The differential diagnosis of poorly differentiated SNSCC is challenging and includes: SNUC (including those characterized by molecular identifiers, such as IDH2-mutant SNUC, SMARCA4-deficient carcinoma, and SMARCB1/INI1-deficient carcinoma), NECs, and adenoid cystic carcinoma." (PMID 34200193, 2021).
brain cancer (4 papers, 2013 to 2019). A primary or metastatic malignant neoplasm affecting the brain. "In humans, the protein SMARCB1 plays an important role in this process: if damaged or deleted, development will be severely disrupted, sometimes causing brain cancer early in life." (PMID 31033435, 2019).
endometrial carcinoma (4 papers, 2015 to 2019). A malignant tumor arising from the epithelium that lines the cavity of the uterine body. "Recent studies showed inactivation of SWI/SNF complex subunits such as INI1 (SMARCB1), BRG1 (SMARCA4) and ARID1A (BAF250a) whose alterations might help distinguish poorly (grade 3) differentiated endometrial carcinoma from DEAC." (PMID 29545232, 2018).
head and neck cancer (4 papers, 2019 to 2025). A primary or metastatic malignant neoplasm affecting the head and neck. "Still, sinonasal tumors account for only approximately 8% of all head and neck tumors, and SMARCB1-deficient tumors in head and neck cancer are rare." (PMID 39398818, 2024). "There is no standard treatment for head and neck cancer with SMARCB1-deficient tumors, and multidisciplinary treatments, such as surgery, cisplatin-based chemotherapy, and radiation, have been performed." (PMID 39398818, 2024).
myoepithelioma (4 papers, 2008 to 2025). "Other subgroups of myoepithelial tumors of soft tissue are associated with alternative genetic aberrations such as rearrangements of other genes (e.g., PLAG1) or homozygous deletion of the INI1/SMARCB1 gene, while in a large proportion, the genetic background is not yet known." (PMID 31049020, 2019).
neurofibromatosis type 2 (4 papers, 2019 to 2025). "A diagnosis of neurofibromatosis type II and schwannoma predisposition syndrome was initially considered but screening of NF2, INI1, SMARCB1, and LZTR1 on the patient’s blood using NGS did not reveal any detectable germline alteration." (PMID 31796102, 2019).
renal carcinoma (4 papers, 2018 to 2025). A carcinoma arising from the epithelium of the renal parenchyma or the renal pelvis. "The diagnosis of renal carcinoma with SMARCB1 deficiency remains challenging due to the rarity of this neoplasm and the nonspecific initial symptoms, which may mimic lower urinary tract diseases." (PMID 40777608, 2025). "Immunohistochemical study showed positivity for PAX8 and deficiency of INI-1 (SMARCB1) expression, consistent with Renal Carcinoma with INI-1 deficiency." (PMID 40777608, 2025).
thoracic neoplasms (4 papers, 2022 to 2025). "In the setting of thoracic neoplasms, it has been described that SMARCA4 loss correlates with poorer outcome and expression of SOX2, CD34, and SALL4, and SMARCB1 loss is mainly seen in thoracic neoplasms of a mesenchymal lineage." (PMID 39125735, 2024). "In our cohort, immunohistochemical INI1 (SMARCB1) deficient thoracic neoplasms occurred in one woman and eight men, ranging from 20 to 76 years of age (mean 57 years) at disease presentation." (PMID 35864317, 2022).
undifferentiated sarcoma (4 papers, 2013 to 2024). "We compared these findings with a model of undifferentiated sarcoma, CLF_PEDS015T, that does not harbor mutations in SMARCB1." (PMID 30860482, 2019).
bladder tumor (3 papers, 2020 to 2025). "Recently, SMARCB1 (switch/sucrose nonfermentable-related matrix-associated actin-dependent regulator of chromatin subfamily B member 1), which encodes INI-1 (integrase interactor 1) loss, was found to drive bladder tumor progression via activation of the IL6/STAT3 axis." (PMID 39273033, 2024). "Autopsy with subsequent immunoprofile and molecular testing were crucial in establishing the absence of INI1 nuclear expression and possible homozygous deletion of SMARCB1 in the urinary bladder tumor tissue." (PMID 33344321, 2020).
chronic myeloid leukemia (3 papers, 2017 to 2024). "Deletions of SMARCB1 are frequent in patients with chronic myeloid leukemia." (PMID 38382674, 2024).
gastric carcinoma (3 papers, 2021). A carcinoma that arises from epithelial cells of the stomach. "In summary, the expression of SMARCB1, does not appear to be of major importance in gastric carcinoma." (PMID 34359794, 2021). "As in adenocarcinomas of the lung and esophagus, no case with complete loss of SMARCB1 could be detected, suggesting that this subunit of the SWI/SNF complex does not play an overly important role in gastric carcinomas." (PMID 34359794, 2021).
leukemia (3 papers, 2021 to 2023). A malignant (clonal) hematologic disorder, involving hematopoietic stem cells and characterized by the presence of primitive or atypical myeloid or lymphoid cells in the bone marrow and the blood. "Inactivating mutations of BRG1/SMARCA4, SNF5/SMARCB1, BCL11B, and the BAF complex subunits SMARCA2 and ARID1A are prevalent in leukemia." (PMID 33468999, 2021). "In contrast, LOF of cBAF (Smarcd2 and Smarcb1 knockouts), MLL4-COMPASS (Kmt2d knockout) and Prmt1 pushed leukemia toward basophil and erythroid fates." (PMID 37580596, 2023).
liposarcoma (3 papers, 2015 to 2025). A usually painless malignant tumor that arises from adipose tissue. "Frequently encountered alterations include MDM2 amplification for well-/dedifferentiated liposarcomas, MYC amplification for radiation induced angiosarcoma or segmental chromosomal deletions on chromosome 22q encompassing SMARCB1 for rhabdoid tumours." (PMID 33479225, 2021).
mesothelioma (3 papers, 2018 to 2022). A usually malignant and aggressive neoplasm of the mesothelium which is often associated with exposure to asbestos. "Few mesothelioma cases were reported harboring loss of INI1 (SMARCB1) protein expression, but these retained positivity for common mesothelial markers." (PMID 35864317, 2022).
pineoblastoma (3 papers, 2023 to 2026). Pineoblastoma is a rare, malignant type of supratentorial primitive neuroectodermal tumor (sPNET), found mainly in children (less than 10% of cases are reported in adults), and located in the pineal region of the brain but that can metastasize along the neuroaxis. "There is no loss of SMARCB1/INI1 staining in pineoblastomas, a useful feature to distinguish them from atypical teratoid rhabdoid tumors." (PMID 38592098, 2024).
T-cell prolymphocytic leukemia (3 papers, 2021 to 2024). A slow-growing type of leukemia (blood cancer) in which too many lymphocytes are found in the bone marrow and/or blood. "Finally, recurrent loss of chromosome 22q11 (which encompasses SMARCB1) has been reported in up to 55% of T-cell prolymphocytic leukemias (T-PLL) (combined N = 34), but SMARCB1 may not be significantly downregulated in the affected cases." (PMID 36810086, 2023).
vulval neoplasms (3 papers, 2020 to 2025). "Additionally, SMARCB1 mutations have also been described in other malignancies of the female genital tract as undifferentiated endometrial carcinoma and vulval neoplasms." (PMID 35200537, 2022). "MELTVR represents one of SMARCB1-deficient vulvar neoplasms." (PMID 31915021, 2020).
acute myeloid leukemia (2 papers, 2023 to 2024). Acute myeloid leukemia (AML) is a group of neoplasms arising from precursor cells committed to the myeloid cell-line differentiation. "Loss of SMARCB1 has been shown to promote acute myeloid leukemia cell migration and survival." (PMID 38382674, 2024).